CDH1 (cadherin 1)
Diseases named in the same sentence as CDH1 in open-access papers (continued):
Sharing a sentence is not in itself a finding about the gene and the disease.
tumor (continued). "In addition to SPINT2, four further genes (CDH1, PLAU, IGFB3 and MT1G) had previously been reported to undergo promoter region hypermethylation in RCC tumours." (PMID 18195710, 2008). "Moreover, in pRCC, CDH1 and RASSF1A methylation levels correlated negatively with tumor stage and grade, respectively." (PMID 17645803, 2007). "In the group of IDCs, CDH1 promoter methylation was found in 1 tumor showing absence of E-cadherin expression and in 45 weakly positive tumors (scores 1+ and 2+)." (PMID 16512896, 2006). "Interestingly, 8p23.2 was also more frequently deleted in BRCA mG3 tumors although the EMT signature was upregulated in mG1, suggesting that CDH1 inactivation and CSMD1 deletion might be two independent mechanisms for tumor metastasis." (PMID 40740860, 2025). "Moreover, in DNA methylation alterations of tumor cells induced by GLP-1RAs, studies have demonstrated that during breast cancer progression, tumor suppressor genes such as ESR1, CDH1, and ADAM33 are downregulated due to hypermethylation alterations in their promoter regions." (PMID 40140925, 2025). "This revealed that tumor cells in MBMs not only exhibited significantly upregulated tumorigenesis and maintenance genes (e.g., MET and TBX2), but also expressed neural differentiation markers (e.g., NRG3, NELL1, NCAM1, ADNP) and cell adhesion molecules (e.g., CDH1, PRKCA)." (PMID 41284647, 2025). "Methylation of CpG islands at the promoter site has been observed in different tumor cells and has become one of the hallmarks of many cancers because of its ability to silence a number of tumor suppressor genes, including P15INK4b, P16INK4a, P14ARF, CDH1, and other genes." (PMID 40760406, 2025). "This negative correlation suggests that higher CDH1 expression may contribute to tumor stability and cohesion, consistent with its role as a tumor suppressor and adhesion molecule." (PMID 41048343, 2025). "Altered molecular targets, such as E-cadherin (CDH1), MMP9, Survivin (BIRC5), Cytokeratin 5 (KRT5), VEGFA, IL15, TNF-α (TNF), TRAIL (TNFSF10), and Tenascin-C (TNC), exhibited increased expression in our study, which correlates with their upregulation in tumor samples from individuals with OC." (PMID 40072102, 2025). "Hence, high NFIB levels lead to expansion of a poorly differentiated E-cadherin (CDH1)-negative invasive tumor subpopulation, which consequently correlates with worse patient survival." (PMID 38395864, 2024). "Additionally, HBx inhibits the expression of the E-cadherin gene (CDH1) by activating TGF-β, which may be an additional mechanism for its downregulation of E-cadherin and promotion of tumor metastasis." (PMID 38962270, 2024). "Furthermore, the western blotting results showed that CDH1 expression was not significantly different between the recurrent and primary tumours, whereas increased expression of CDH2 was observed in the recurrent ACP group." (PMID 38594611, 2024). "Because EMT initiation is a critical process in tumour progression, we evaluated the effect of BEST4 on EMT using quantitative polymerase chain reaction (qPCR) and found that BEST4 expression upregulated CDH1 and TJP1 and downregulated VIM and TWIST1 in HCT116 compared with the control (p<0.05)." (PMID 39699952, 2024). "Additionally, it is involved in tumor energy metabolism, angiogenesis, and apoptosis, which may help DLBCL cells survival.Cadherin 1 (CDH1) codes for calcium-dependent cell adhesion proteins." (PMID 37716978, 2023).
tumor (continued). "Indeed, it is important to note that SW1736 cells show high levels of PAX8, FOXE1 and CDH1, compared to KTC2, indicating ATC tumor heterogeneity that may influence the response to EZH2 modulation." (PMID 37175580, 2023). "Given that APC/Cdh1 is critical to the function of HR repair factors, we hypothesize that tumor cells lacking Cdh1 will be as sensitive to replication pressure as cells without BRCA1." (PMID 35627188, 2022). "Therefore, tumor cells lacking Cdh1 are very likely sensitive to DNA damage and to drugs that induce replication stress such as PARPi." (PMID 35627188, 2022). "Furthermore, the HLA-DMA and HLA-DMB genes are expressed at high relative levels, similar to those for CDH1 (epithelial cells) and CD68 (macrophages), suggesting that they may be expressed by these cell types within the tumor." (PMID 36497170, 2022). "We identified ZNF471 as a novel potential tumor suppressor gene in CC that inhibits cancer cell growth, proliferation, invasion, and metastasis by arresting cell cycle progression and induction of EMT by up-regulation of CDH1 and downregulation of CDH2, VIM, and TW1." (PMID 33566221, 2021). "The results suggest that CDH1 and HIN1 methylation heterogeneity may increase tumor metastasis." (PMID 34539742, 2021). "Analysis of Molecular Signatures DB (MSigDB) revealed that spindloid tumours were predominantly linked to stemness, EMT, and invasive gene signatures, while differentiation, Cdh1 (E-Cadherin), and cell junction gene signatures were enhanced in non-spindloid tumours." (PMID 33772015, 2021). "Regarding the six tumors with downregulation of CDH1 gene, they were characterized by the absence of promoter methylation in all normal and tumor tissues, with the exception of one case (17/11) that showed partial methylation of all the CpG sites analyzed in both normal and tumor tissues." (PMID 34066170, 2021). "Moreover, 64% (25 of 39) tumor tissues with high miR-25 levels showed negative CDH1 expression; whereas only 36.3% (12 of 33) tumor tissues of low miR-25 level were CDH1 negative." (PMID 31208279, 2019). "In addition, Spearman correlation coefficient analysis showed that there was a significant negative correlation between TRERNA1 and CDH1 in metastatic tumour cases but not in non‐metastatic cases." (PMID 31012192, 2019). "RP11-169D4.1 is targeted and inhibited by miR-205-5p.The long non-coding RNA RP11-169D4.1 may serve as a tumor suppressor and a promising therapeutic target in laryngeal cancer, since it could inhibit the process of EMT by regulating CDH1, a well-established tumor suppressor." (PMID 31336999, 2019). "Our results support the hypothesis that somatic mutations in CDH1 or CTNNB1 are not a major contributor to cancer cell detachment, and thus play a limited role in the etiology of tumor metastasis." (PMID 29156750, 2017). "In keeping with most studies finding a correlation of abnormal E-cadherin expression with adverse clinicopathologic factors, tumours with CDH1 structural alterations displayed a significantly poorer survival rate than tumours negative for CDHI alterations or tumours with epigenetic CDH1 alterations." (PMID 27514667, 2016). "Similarly, CDH1 expression was slightly higher in 24 (54.5%) tumor samples although no statistical difference was found (P = 0.47)." (PMID 26334097, 2015). "Heterozygous mice (Cdh1+/−) develop normally and show no increased tumor incidence, suggesting that either E-cadherin haploinsufficiency does not induce tumors, E-cadherin loss is not tolerated and/or that the lifespan of the mouse is not sufficient to allow evolutionary loss of heterozygosity." (PMID 25757734, 2015).
tumor (continued). "Interestingly, we found that the expression of CRF2 ligands is inversely correlated to epithelial differentiation markers like E-cadherin (Cdh1) but correlated to mesenchymal makers like vimentin (Vim), suggesting a role of CRF2 in the cellular disorganization observed during tumor progression." (PMID 24260200, 2013). "When the activity of CDH1 is normal, tumor cells are not easily detached from the primary tumor." (PMID 22514028, 2012). "We speculated it may because peritoneal washes contained some non-tumor cells, and we did not use laser capture microdissection to purify target cells, which remarkably affected the rate of CDH1 methylation." (PMID 22514028, 2012). "When the healthy and tumor groups were reorganized according to the patients’ age range (≤65 or >65 years old) and the patients’ gender (male or female), no statistically significant differential expression of CDH1 and VIM transcript levels were observed (p > 0.05)." (PMID 40305202, 2025). "Taken together, our data support a model in which EZH2 overexpression drives HB tumor progression through both canonical and noncanonical mechanisms, associated with dysregulated mitosis, altered PRC2 complex integrity, and potential epigenetic modulation of CDH1 signaling." (PMID 40766612, 2025). "Taking the results of CDH1 expression in Ta/T1 stage BC, we speculate that CDH1 is markedly up-regulated from the initiation tumor stage but not further altered during the tumor development phase, making the value of CDH1 in prediction of BC more prominent than other hub genes." (PMID 36131343, 2022). "Given the results of CDH1 expression in patients with Ta/T1 stage BC, we speculate that CDH1 is markedly up-regulated in the tumor initiation stage but not further altered during the tumor development phase." (PMID 36131343, 2022). "E-cadherin (CDH1) plays an important regulatory role in cell proliferation, cell adhesion, cell polarity and epithelial-mesenchymal transition and other physiological processes, and its disorder may promote tumor proliferation, invasion, migration and transfer." (PMID 34692659, 2021). "In addition, tumor cells exhibited elevated ITGA5 and VIM levels and reduced integrin β1 (ITGB1) and CDH1 levels after suspended coculture with CAFs in MUs, thus indicating that interaction with CAFs in MUs could further maintain the ITGA5high mesenchymal phenotype in ATCs." (PMID 30710055, 2019). "Likewise, the tumor-suppressor sirtuin gene SIRT2 was shown to promote APC/C-Cdh1 function through acetylation of Cdh1, and again may explain tumor-suppresive effects of indirect APC/C-Cdh1 inactivation." (PMID 26650195, 2016). "However the increased E-cadherin levels was not matched with increased transcription of Cdh1 in the SG-/- tumour cells suggesting that serglycin may have a role in E-cadherin degradation during tumour progression." (PMID 27223472, 2016). "The different distribution of APC-free and APC-bound Cdh1 in primary somatic cells versus tumor cells further indicates that Cdh1 might function differently via an APC-dependent or APC-independent mechanism in different cellular contexts, such as somatic versus tumor cells." (PMID 27462441, 2016). "Moreover, the expression of E-cadherin (CDH1), a negative-related protein for tumor invasion, was clearly reduced, and two positive-related proteins for tumor invasion and metastasis, MMP-2 and MMP-9, were increased in expression in the IgGhigh MDA-MB-231 cells." (PMID 26472025, 2015). "However, we pay attention to the fact that accumulation of gene methylation actually shows an increased risk of carcinogenesis as many studies have indicated, even if methylation of CDH1 may not directly affect the tumor development." (PMID 23280118, 2013).
tumor (continued). "In the present study, the methylation pattern of the CDH1 gene was not correlated with the age of patients at diagnosis suggesting that they are not due to age-related methylation changes but probably is correlated with the deregulation of the methyltransferase activity during tumor progression." (PMID 16512896, 2006). "While no change in CDH1 and CDH2 expression was detected in the primary tumor tissue compared to normal colon tissue, vimentin SNAIL and TWIS showed high expression in the tumor tissue." (PMID 40566531, 2025). "We found that PCS increased the number of mitophagosomes in tumour‐conditioned RAW264.7 cells, and the overexpression of Cdh1 decreased the number of mitophagosomes with or without PCS treatment." (PMID 40604335, 2025). "The antitumour efficacy of bispecific antibodies plus talazoparib was not improved in the tumours that were insensitive to EGFR blockade, corresponding to the high expression of VIM and FN1 genes and relatively low expression of CDH1 and CLDN7 genes." (PMID 37441599, 2023). "In contrast, the expression level of CDH1 and EGF (P-value of < 0.01 and < 0.05, respectively) were significantly lower in the tumor tissues group rather than those found in adjacent normal tissues." (PMID 36284226, 2022). "The EM033 cells, derived from a stage IA tumor with dedifferentiated endometrioid histology, displayed a high EMT status, characterized by absence of E-cadherin (CDH1) and cytokeratin (KRT) and the presence of vimentin (VIM) on both protein and mRNA level." (PMID 34936030, 2021). "No negative correlations were detected between expressions of CDH1 and any of EMT genes in tumor, LNM and CTC samples." (PMID 35008529, 2021). "While neither body weight nor tumor weight showed statistical difference between the control and the DDR1-IN-1 mice, results of the CDH1/PDPN dual immunohistochemical stained sections from two groups were distinct." (PMID 32244515, 2020). "This adds FST to the short list of metastasis suppressor genes, such as breast cancer metastasis suppressor-1 (BRMS1), cadherin-1 (CDH1), and nucleoside diphosphate kinase 1 (NM23), that inhibit metastasis formation without impacting primary tumor growth." (PMID 28583174, 2017). "In contrast to CDH1, cases positive for methylation of CDKN2A promoter in tumor tissues were much less even in long-DM (30%) and in non-DM (10%)." (PMID 29273724, 2017). "The Spearman analysis showed that CDH1, CTNNB1 were significantly relevant with tumour sizes (p = 0.03) and clinical stage (p < 0.001) not age (p = 0.461), gender (p = 0.335), smoking (p = 0.224)." (PMID 29115924, 2017). "Yet, patient 7 showed an opposing result by not presenting methylation on the tumor for genes DAPK and CDH1; these genes were methylated only in the respective adjacent margins (7PM and 7DM)." (PMID 26363785, 2015). "In this paper, Migdalska-Sek at al. assessed and compared the methylation level of 8 tumor suppressor genes, ARHI, CDH1, KCNQ1, MEST, p16INK4A, RASSF1A, SLC5A8 and VHL in PTC tumor tissues and matched adjacent noncancerous thyroid tissues." (PMID 25490036, 2014). "In contrast, residual tumor cells in the Wnt1 model did not exhibit increased expression of mesenchymal markers and instead displayed increased expression of the basal epithelial marker Krt14 (CK14) along with luminal epithelial markers Epcam and Cdh1." (PMID 34088357, 2021).
tumor (continued). "Additionally, both samples were also analyzed by Multiplex Ligation-dependent Probe Amplification (MLPA) in the tumor DNA (probe SALSA P083-C2 CDH1, MRC Holland) and no major CDH1 deletions were found." (PMID 30642281, 2019). "However, these two basal/SCC‐like tumour categories do not differ in their KRT5, KRT14/FOXA1, GATA3 ratios, their defining characteristics, or their shifts to high CDH3 and lower CDH1 expression." (PMID 28195647, 2017). "Gene expression changes between tumor with and without gene deletions were negative for MAP2K4 (fold change = −2.37, p = 0.0099), PTEN (fold change = −1.71, p = 0.10) and CDH1 (fold change = −1.59, p = 0.22), but close to one for RB1 (fold change = 1.08, p=0.62)." (PMID 26910888, 2016). "Expression level of FCGR1A, although not correlated with VIM or CDH1, had r = 0.31 and r = 0.42 with SNAI1 and SNAI3 respectively, suggesting it may be co-expressed with these EMT drivers in some tumours." (PMID 27876705, 2016). "Hence, although FN1 and CDH1 are presumably not the key markers involved, these findings supported the view that the role of IGF2BP1 in promoting tumor cell migration and sustaining mesenchymal-like cell morphology involves the upregulation of LEF1 and SNAI2." (PMID 23677615, 2013). "Similarly, our findings also showed that 3 of 6 genes had significantly higher methylation level in tumor tissues than nonmalignant lung tissues, including CALCA, CDH1, and PAX6 genes." (PMID 21639921, 2011). "Indeed, Cdh1 appeared to be expressed at comparable levels in IT and IC1 tumor lesions regardless of Dsp status." (PMID 20862307, 2010). "E-cadherin downregulation is not specific to ILC, as it also occurs during progression to high-Ki67 IDC tumors such as basaloid and triple-negative subtypes, reflecting dynamic epigenetic trans-repression of CDH1 at the invasive tumor front as part of epithelial-mesenchymal transition (EMT)." (PMID 25385074, 2014). "Moreover, a comparison between PSBMA@threads and commercial silica membrane solid-phase extraction materials revealed that PSBMA@threads can extract DNA from 1 × 105 tumor cells for PCR amplification of GAPDH and CDH1, whereas the silica membrane purification column could not." (PMID 40573538, 2025). "Furthermore, we observed comparable upregulations of CDH1 in both ATC01 spheroids and parental tumor samples, whereas no such upregulation occurred in monolayer-cultured cells, suggesting our spheroid model cultures may mimic more closely the in vivo behavior related to the EMT status." (PMID 38500204, 2024).